OXSR1 (oxidative stress responsive kinase 1)
Description:
Effector serine/threonine-protein kinase component of the WNK-SPAK/OSR1 kinase cascade, which is involved in various processes, such as ion transport, response to hypertonic stress and blood pressure. Specifically recognizes and binds proteins with a RFXV motif. Acts downstream of WNK kinases (WNK1, WNK2, WNK3 or WNK4): following activation by WNK kinases, catalyzes phosphorylation of ion cotransporters, such as SLC12A1/NKCC2, SLC12A2/NKCC1, SLC12A3/NCC, SLC12A5/KCC2 or SLC12A6/KCC3, regulating their activity. Mediates regulatory volume increase in response to hyperosmotic stress by catalyzing phosphorylation of ion cotransporters SLC12A1/NKCC2, SLC12A2/NKCC1 and SLC12A6/KCC3 downstream of WNK1 and WNK3 kinases. Phosphorylation of Na-K-Cl cotransporters SLC12A2/NKCC1 and SLC12A2/NKCC1 promote their activation and ion influx; simultaneously, phosphorylation of K-Cl cotransporters SLC12A5/KCC2 and SLC12A6/KCC3 inhibit their activity, blocking ion efflux. Acts as a regulator of NaCl reabsorption in the distal nephron by mediating phosphorylation and activation of the thiazide-sensitive Na-Cl cotransporter SLC12A3/NCC in distal convoluted tubule cells of kidney downstream of WNK4. Also acts as a regulator of angiogenesis in endothelial cells downstream of WNK1. Acts as an activator of inward rectifier potassium channels KCNJ2/Kir2.1 and KCNJ4/Kir2.3 downstream of WNK1: recognizes and binds the RXFXV/I variant motif on KCNJ2/Kir2.1 and KCNJ4/Kir2.3 and regulates their localization to the cell membrane without mediating their phosphorylation. Phosphorylates RELL1, RELL2 and RELT. Phosphorylates PAK1. Phosphorylates PLSCR1 in the presence of RELT.
Synonyms: KIAA1101; OSR1
Tractability: Small molecule: a structure with a bound ligand is known; a high-quality ligand is known; it has a high-quality binding pocket; it belongs to a druggable protein family. PROTAC: ubiquitination databases record sites on it; its protein half-life has been measured; a small molecule that binds it is known.
Target class: STE protein kinase STE20 family; Protein Kinase; Enzyme; Kinase; STE protein kinase FRAY subfamily; STE protein kinase group
Gene: Protein-coding gene on chromosome 3 (38,165,089 to 38,255,484, forward strand). Ensembl gene ENSG00000172939.
Subcellular location: Cytoplasm
Subcellular location (Human Protein Atlas): Cytosol
Gene Ontology:
Molecular function: ATP binding; identical protein binding; ion channel regulator activity; magnesium ion binding; protein binding; protein kinase binding; protein serine kinase activity; protein serine/threonine kinase activity; scaffold protein binding; transmembrane transporter binding; transporter regulator activity; potassium channel inhibitor activity; protein kinase activity
Biological process: cell volume homeostasis; cellular hyperosmotic response; cellular response to chemokine; chemokine (C-X-C motif) ligand 12 signaling pathway; intracellular signal transduction; osmosensory signaling pathway; positive regulation of T cell chemotaxis; protein autophosphorylation; protein phosphorylation; renal sodium ion absorption; signal transduction; cellular hypotonic response; chemokine (C-C motif) ligand 21 signaling pathway; regulation of potassium ion transmembrane transport; response to oxidative stress; response to xenobiotic stimulus
Cellular component: cytoplasm; cytosol; extracellular exosome
Genetic constraint (gnomAD): Loss-of-function variants: 4 observed, 15.96 expected, observed/expected ratio (o/e) 0.25, 90% interval 0.12 to 0.57. The upper end of that interval is the gene's LOEUF score, 0.57, which puts it in group 2 of 6, group 1 being the genes least tolerant of losing a copy. Missense variants: 135 observed, 177.65 expected, observed/expected ratio (o/e) 0.76, 90% interval 0.66 to 0.88. Synonymous variants: 72 observed, 63.13 expected, observed/expected ratio (o/e) 1.14, 90% interval 0.94 to 1.39.
Homologues: Orthologues: chimpanzee OXSR1 (99% identical), macaque OXSR1 (99% identical), dog OXSR1 (97% identical), guinea pig OXSR1 (97% identical), mouse Oxsr1 (96% identical), rat Oxsr1 (92% identical). Paralogues in human: STK39 (75% identical), MAP4K4 (32% identical), TNIK (31% identical), MAP4K3 (30% identical), MINK1 (30% identical), SLK (30% identical), STK10 (30% identical), STK24 (29% identical), STK26 (29% identical), MAP4K5 (28% identical), STK25 (28% identical), TAOK1 (28% identical), and 23 more.